INS (insulin)
Diseases named in the same sentence as INS in open-access papers (continued):
Sharing a sentence is not in itself a finding about the gene and the disease.
diabetes (continued). "There are several PNPs, including polysaccharides or protein-based NPs, COFs, and others, that have demonstrated pH-sensitive insulin release for diabetes therapy." (PMID 38167129, 2024). "Although both GIP and GLP-1 stimulate insulin secretion, their effects differ in type 2 diabetes mellitus (T2DM)." (PMID 39479116, 2024). "T1D had a greater body mass index (27.7 [5.7] vs 23.1 [3.2] kg/m2), LDL Cholesterol, and estimated GFR, and had a mean A1c of 7.4 [1.0] % (57 mmol/mol) and diabetes duration of 16.1 [3.7] years with 56% using insulin pumps." (PMID 38789969, 2024). "Diabetes is one of the world's most widespread metabolic illnesses, characterised by faulty insulin release." (PMID 38357071, 2024). "For the first time there is an opportunity to make an important breakthrough in basal insulin therapy, particularly in people with type 2 diabetes, and to improve not only the quality of life of people with diabetes, but also the practice of diabetologists." (PMID 38679644, 2024). "Some of them are used for the treatment of diabetes mellitus (type 1 and 2) and/or obesity: insulin detemir (Levemir®), insulin degludec (Tresiba®), liraglutide (Victoza®/Saxenda®), and semaglutide (Ozempic®, Rybelsus®, Wegovy®)." (PMID 38732194, 2024). "Anthocyanidins also have been shown to improve glucose metabolism and insulin sensitivity, which is critical for controlling blood sugar in diabetics." (PMID 39529845, 2024). "We also found that at equivalent amounts of RyR2 protein from diabetes rats, the heart bound less [3H] ryanodine activity compared with control rats; insulin and Rb1 treatment increased the [3H] ryanodine activity." (PMID 38961333, 2024). "The limitations of organ transplantation, including donor shortages and the requirement for immunosuppressive drugs, make regular insulin administration the primary treatment for diabetes." (PMID 39279997, 2024). "We report the case of a patient with type 2 diabetes mellitus (T2DM) on insulin therapy with a history of recurrent and severe hypoglycemia related to lipodystrophy with an uncommon clinical presentation." (PMID 39691127, 2024). "Diabetes mellitus is characterized by insulin resistance (IR) and dysfunctional insulin secretion from pancreatic β-cells." (PMID 39436903, 2024). "Several studies have suggested that the duration of diabetes or insulin treatment were related to the development of AF." (PMID 38172896, 2024). "Type 2 diabetes mellitus is a disease in which insulin action is impaired, and an acute bout of strength exercise can improve insulin sensitivity." (PMID 38805474, 2024). "This system can modulate glucose metabolism and be a potential therapeutic target for diabetes by enhancing insulin secretion." (PMID 38326874, 2024). "Diabetes mellitus (DM) is a metabolic disorder characterized by hyperglycaemia due to abnormal insulin production or functionality." (PMID 39350473, 2024). "Based on these factors, China's COVID-19 Suggestions for Glucocorticoid Use clearly indicate that in patients with diabetes receiving oral hypoglycemic agents or insulin treatment, glucocorticoid use should be carefully considered when treating COVID-19." (PMID 38975064, 2024). "For example, Roseburia intestinalis promotes the production of IL-22 an anti-inflammatory cytokine, while attenuating insulin resistance and the development of diabetes." (PMID 39070791, 2024). "Downregulated levels of SERCA2b were observed in INS-1E cells after exposure to high glucose concentrations in vitro as well as in experimental models of diabetes, resulting in diminished insulin secretion and Ca2+ homeostasis impairment." (PMID 39594609, 2024). "Diabetes mellitus is a chronic metabolic disease that is characterized by high blood sugar levels and circulation insulin, leading to significant morbidity and mortality worldwide." (PMID 39125375, 2024).
diabetes (continued). "The use of insulin pens has changed the lives of millions of people who suffer from diabetes as they are safe, simple to use, convenient, efficient, and less painful than conventional vials and syringes." (PMID 38559691, 2024). "To date, the literature on smart insulin pens has focused on assessing patient preference, ease of use, and technical accuracy, investigating the preference choice for people with diabetes." (PMID 39791645, 2024). "The mean number of anti-diabetes medications was 2.1 ± 0.9 items, and 45% (18/40) of patients used insulin." (PMID 39610482, 2024). "An accurate review of insulin secretion and the complex neurohormonal regulation of glycemia in physiology and diabetes was reported in the review of G.D. Dimitriadis and coauthors." (PMID 39519472, 2024). "Michael Somogyi was a pioneer in the administration of insulin to patients with diabetes in the United States and in devising a method for insulin production." (PMID 39718705, 2024). "The beneficial role of SCFAs on host metabolic health has been documented in numerous studies, encompassing obesity control, improved insulin sensitivity, and deceleration of diabetes progression (31, –, 33)." (PMID 38411058, 2024). "Other factors including oxidative stress, gradual malfunctioning in gene expression of insulin and other beta‐cells, persistent endoplasmic reticulum strain, and morphological transformation of membranous mitochondria, also contribute to diabetes." (PMID 38628217, 2024). "The Type 2 diabetes mellitus is characterized by reduced insulin secretion from the β-cells of the pancreas, increased insulin resistance, and disruption of incretin secretion." (PMID 38474087, 2024). "In this study, men showed significantly high prevalences of diabetes, hypertension and dyslipidemia, high levels in fasting glucose, HbA1c, insulin, total cholesterol, LDL, and TG and low levels in HDL compared to women." (PMID 39595856, 2024). "Canine bone marrow-derived mesenchymal stem cells represent a potential starting source for the in vitro generation of functional insulin-producing cells that can be used in the clinical setting for treating diabetes mellitus type 1 in humans and dogs." (PMID 39195834, 2024). "Diabetes is a metabolic disorder distinguished by persistent hyperglycemia resulting from impaired insulin secretion, insulin action (sensitivity), or a combination of the two." (PMID 39072261, 2024). "Diabetes mellitus is characterized by persistent hyperglycemia because of reduced pancreatic β-cell secretion of insulin, insulin sensitivity in peripheral tissues, or both." (PMID 39234180, 2024). "Changes in ambulatory glucose profile in patients with type 1 diabetes mellitus after switching from sensor-augmented insulin pump therapy to a do-it-yourself artificial pancreas system: a retrospective data analysis of real-world data." (PMID 39196351, 2024). "Verapamil, an antihypertensive calcium channel blocker, demonstrated the survival of insulin-producing beta cells and reversal of diabetes in mouse models." (PMID 39568817, 2024). "Key evidence linking diabetes to AD emphasizes critical metabolic processes that contribute to neurodegeneration, including inflammation, oxidative stress, and alterations in insulin signaling pathways." (PMID 39596023, 2024). "The efficacy of dulaglutide vs. insulin in improving the metabolic control of diabetes comprised the primary end-point, but renal outcome has also been carefully evaluated." (PMID 39684653, 2024). "Although luteolin was weakly correlated with DR in previous research, it manifests a positive impact on metabolic disorders like diabetes and obesity by modulating glucose metabolism and insulin sensitivity." (PMID 38633216, 2024). "Dietary administration of Fe3O4 NPs has positive effects in treating high blood glucose and excess insulin levels in genetic manipulation or a high-glucose diet-induced diabetes Drosophila model." (PMID 38711066, 2024).
diabetes (continued). "We included 3164 patients of which 323 had diabetes, including 186 treated with insulin and antidiabetic medicine, 35 with insulin only and 102 with antidiabetic medicine only." (PMID 38849653, 2024). "These approaches laid the groundwork for understanding dietary impacts on diabetes before the advent of insulin therapy." (PMID 39691108, 2024). "Herein, we present a case of a 33-year-old woman with a medical history of type 1 diabetes mellitus (treated with insulin), arterial hypertension, and obesity." (PMID 39156365, 2024). "Benfluorex used to be a clinical diabetes medicine by activating HNF4α, which also improved levels of insulin and FFA affected by atorvastatin treatment, as well as fasting glucose." (PMID 38970167, 2024). "Previous research on potential interactions between topiramate and diabetes medication other than insulin reported a modest increase in metformin exposure and decrease in topiramate exposure following their coadministration." (PMID 38347465, 2024). "Nevertheless, in insulin treated patients more diabetes-related morbidities occurred after fast-track hip and knee arthroplasty, particularly concerning cardiac complications." (PMID 38849653, 2024). "Diabetes mellitus, a complex metabolic disorder characterized by impaired insulin production or function, poses significant challenges in its treatment." (PMID 38931040, 2024). "Higher protein intake has been shown to improve insulin sensitivity and enhance glucose uptake, reducing glycemic variability that negatively affects both cognitive function and diabetes management." (PMID 39599676, 2024). "DPP-4 is an important enzyme involved in the regulation of insulin secretion and glucose metabolism; therefore, its inhibitors are of great significance in the treatment of metabolic diseases such as diabetes mellitus." (PMID 39596859, 2024). "An inability to maintain normal blood sugar levels in the body due to inadequate insulin production or insulin resistance can lead to a metabolic disorder known as diabetes." (PMID 39139674, 2024). "Novel technologies, such as automated insulin delivery systems, have substantially impacted the quality of life and the diabetes balance of these patients worldwide." (PMID 39735069, 2024). "Inadequate insulin management, illness, the onset of diabetes, and other metabolic stresses are the most common triggering factors for both disorders." (PMID 38800154, 2024). "Herein, we present the pharmacology of AKS-107 that demonstrates specific targeting of insulin-reactive B cells and efficacy in preventing diabetes in NOD and VH125Tg/NOD mice." (PMID 38515750, 2024). "Dragon fruit’s potential to enhance insulin sensitivity, regulate blood glucose levels, and manage lipid profiles positions it as a promising candidate for diabetes treatment." (PMID 39683835, 2024). "Diabetes is a long-term metabolic disorder characterized by elevated blood sugar levels (hyperglycemia) resulting from insufficient insulin production and/or inefficient insulin use." (PMID 38675143, 2024). "Direct comparisons between these studies should be interpreted with caution, however, as our current study focused on the nationwide insulin‐treated adult diabetes population instead of a sample of the entire diabetes population." (PMID 38273701, 2024). "Research studies have provided insights into the potential benefits of intranasal insulin treatment for individuals with diabetes, including improved learning and memory functions, enhanced hippocampal neurogenesis, and increased brain insulin levels." (PMID 39220736, 2024). "Diabetes mellitus refers to metabolic disorders characterized by chronic high blood glucose levels (hyperglycemia) resulting from defects in insulin secretion, insulin action, or both." (PMID 38686257, 2024). "In Zucker diabetic fatty rats, overexpressing p21 using adenovirus induced p21 mRNA expression and reduced insulin mRNA expression as diabetes developed." (PMID 39684919, 2024).
diabetes (continued). "This holds true for both type 1 (insulin-dependent) and type 2 (non-insulin-dependent) diabetes, as they share comparable behavioural challenges and necessitate similar self-care behaviours." (PMID 38579364, 2024). "The group that received Teach-Back insulin education had higher QoL scores than the group that received standard diabetes education." (PMID 39337195, 2024). "In type 2 diabetes mellitus, insulin resistance impairs the normal vasodilatory function of the endothelium and contributes to glycocalyx damage by interfering with insulin-mediated protective mechanisms on endothelial cells." (PMID 39728298, 2024). "It effectively regulates glycemic levels by stimulating glucose-dependent insulin secretion, and has been developed for the treatment of diabetes." (PMID 38251250, 2024). "For example, an insulin response curve is generally a perfect sigmoid curve, which shifts parallel to the right during aging or during the development of obesity/diabetes, and the right-shift is regarded as a sign of insulin resistance." (PMID 39617270, 2024). "For self-care assessment (SCI-R), there was a score worsening in patients with longer duration of diabetes [OR 1.1 (1.0-1.1)] and in those using insulin [OR 8.3 (1.7-41.4); r 0.23, P = 0.01]." (PMID 39420900, 2024). "Diabetes mellitus (DM) is a metabolic disease characterized with increased blood level of glucose due to the impairment of insulin production and action." (PMID 39372400, 2024). "The optimization of patient experience in the use of diabetes technology is beneficial as the majority of TPIAT patients have long-term insulin requirements." (PMID 40302953, 2024). "Twenty-seven (87%) had pancreatic insufficiency, eight (26%) had carbohydrate intolerance, and seven had CF-related diabetes (22.5%), among which six received insulin treatment (19%)." (PMID 39408260, 2024). "On the other hand, 77.5% in the insulin group reported that they would be concerned if they forgot to take their diabetes medicine, compared to 58.6% in the non-insulin group." (PMID 39587498, 2024). "Half of the patients had diabetes mellitus, with 79 patients taking oral hypoglycemic agents and 20 patients receiving insulin injections." (PMID 39234605, 2024). "Diabetes, a group of metabolic disorders, arises from either an absolute or relative insulin secretion insufficiency and/or dysfunction in insulin utilization and is primarily characterized by hyperglycemia." (PMID 38219272, 2024). "Diabetes digital health solutions offering basal insulin dose titration such as the Tempo system by Lilly (Indianapolis, Indiana, USA) require regulation and are prescribed." (PMID 39351525, 2024). "Nevertheless, because of progressive beta cell function deterioration, insulin remains the mainstay of diabetes treatment for most of these patients." (PMID 39408828, 2024). "Exercise is one of the most effective methods for preventing and managing older people with diabetes, and lifestyle intervention based on regular exercise can improve the insulin sensitivity of patients with diabetes." (PMID 38571669, 2024). "Various treatments have been explored to improve insulin secretion, a key factor in diabetes management." (PMID 39275180, 2024). "Type 2 Diabetes Mellitus (T2DM) is a prevalent subtype of diabetes mellitus characterized by chronic hyperglycemia resulting from reduced insulin sensitivity in individuals." (PMID 38698772, 2024). "Type 2 diabetes (T2D) is the most common type of diabetes and it is depicted by high blood glucose level (or hyperglycemia) resulting from impaired insulin action/secretion or both." (PMID 39070783, 2024). "Recently developed, the Smart MDI system, which combines a CGM with a SIP, offers a comprehensive solution for individuals managing diabetes through insulin injections." (PMID 39411309, 2024). "At 40, pancreatitis episodes exacerbated by pyelonephritis and sepsis led to a diabetes diagnosis, prompting a switch from metformin to insulin." (PMID 38790019, 2024).
diabetes (continued). "Several studies have reported blood-brain barrier (BBB) disruption and insulin resistance in the brain of patients with obesity and diabetes." (PMID 38897158, 2024). "There have been multiple case reports describing adult patients with type 2 diabetes mellitus who experienced decreasing insulin requirements, improving glycated hemoglobin (HbA1c) levels, and/or hypoglycemia after receiving dasatinib [2‐4]." (PMID 39659385, 2024). "Chronic treatment with palmitate induces insulin hypersecretion and later impairment of human islet function and has frequently been used for obese and diabetes modeling in vitro." (PMID 38933536, 2024). "For more over 100 years, insulin has been widely used for its hypoglycemic effect to treat diabetes, and lately the intranasal route has been studied for the administration of insulin." (PMID 39408782, 2024). "It promotes β-cell survival and function, improves insulin sensitivity, modulates gut hormones, and increases β-cell mass, resulting in diabetes remission and better glycemic control in this subgroup of patients with type 2 diabetes." (PMID 39560873, 2024). "As for the history of diabetes mellitus, in the AS group there were two patients with type 1 DM that were treated with insulin, whose glycated hemoglobin levels were 5.7% and 6.7%." (PMID 38731213, 2024). "One patient with diabetes mellitus requiring insulin injections and taking antiplatelet and anticoagulant drugs developed grade 3 hematuria and bladder tamponade after CIRT." (PMID 38778824, 2024). "The current landscape of diabetes management in Morocco predominantly involves conventional pharmacological treatments, such as insulin and oral hypoglycemic agents (e.g., metformin, sulfonylureas), commonly prescribed for type 2 diabetes." (PMID 39452489, 2024). "Unit 1 provides information on diabetes definition and types, insulin function and types, and its regimes." (PMID 38694587, 2024). "Type 1 diabetes mellitus (T1DM) is an autoimmune disease that leads to the destruction of insulin-producing pancreatic beta cells, culminating in absolute insulin deficiency." (PMID 38892513, 2024). "Type 2 diabetes mellitus (T2DM) stands as a prevalent global public health issue caused by deficiencies in the action of insulin and/or insulin production." (PMID 38929747, 2024). "At the time of inclusion, 24.8% of patients had diabetes mellitus, 9.1% were insulin-dependent, and 10.8% were treated with oral antidiabetic drugs." (PMID 39682665, 2024). "A recent study indicates a potential role for RBM20 in cardiovascular complications of diabetes by mediating insulin damage in cardiac tissues." (PMID 38664626, 2024). "In mice with Rfx6 gene deficiency, all endocrine cells are absent, except for polypeptide-secreting cells, resulting in diabetes and early postnatal death, limiting the exploration of its role in beta cell function and INS production." (PMID 39080045, 2024). "Diabetes mellitus (DM) occurs due to chronic hyperglycemia, resulting from insufficient insulin secretion, diminished response, or both." (PMID 39192929, 2024). "Type 2 diabetes mellitus can occur due to damaged insulin secretion by pancreatic beta cells and the inability of insulin-sensitive tissues to respond to insulin." (PMID 38827017, 2024). "Diabetes is a metabolic disorder characterized by chronic hyperglycemia due to defects in the secretion and/or action of insulin that can lead to impaired renal function." (PMID 38738016, 2024). "Results showed that 73% of the diabetes-controlled group didn’t take insulin, while 66.5% of the diabetes-uncontrolled group and 67% of ASCVD were on insulin, vs. 71% in the Southern region." (PMID 39759947, 2024). "In total, 437 patients with diabetes mellitus were included in the study(mean age: 62.5 ± 11.0 years, female: 61.7%, mean diabetes duration:15.3 ± 9.7 years, insulin users: 67.8%)." (PMID 38656030, 2024).